IL6 (interleukin 6)
Diseases named in the same sentence as IL6 in open-access papers (continued):
Sharing a sentence is not in itself a finding about the gene and the disease.
infection (continued). "IL-6 secretion was significantly greater from the aged myoblasts, (age effect: p<0.001), but was not affected by infection or infection over time (infection effect: p=0.600, infection*time interaction effect: p=0.583)." (PMID 26856410, 2016). "The model consists of a number of non-linear ordinary differential equations describing dynamics of pneumococcal population, the inflammatory cytokine IL-6, neutrophils and macrophages fighting the infection and destruction of alveolar tissue due to pneumococcus." (PMID 27196107, 2016). "Similarly, infection with isogenic gingipain mutant strains (ΔRgpA, ΔRgpA/B, ΔKgp) resulted in significantly higher IL-8, IL-6 and MCP-1, compared to stimulation with gingipain-sufficient strain 33277." (PMID 27698456, 2016). "We found that low-dose ND8008 therapy could significantly reduce the initial infection, especially 6–12 hours later in the host serum pro-inflammatory cytokine (IL-1, IL-6 and TNF-α) content." (PMID 26839286, 2016). "Moreover, both, IFN-γ and IL-6 increased upon A. butzleri C1 strain infection (p<0.05 and p<0.001, respectively), but less distinctly for the former as compared to CCUG 30485 strain infection (p<0.05)." (PMID 27438014, 2016). "chagasi-infection, with emphasis on the immunopathogenic role of IL-6 and IL-10 which may aid in preventing or reducing the morbidity of severe AVL." (PMID 27051668, 2016). "Notably, increased IL-6 production of CAR cells has also been observed upon infection with the rodent parasite Toxoplasma gondii." (PMID 28163704, 2016). "A release of IL-6 was similarly triggered by infection with all Francisella strains after 24 h." (PMID 26739172, 2016). "IL-6 is a pleiotropic cytokine released in large amount during infection, autoimmunity and cancer." (PMID 27330885, 2016). "IL-6 and IL-1⍺ were induced 5 hours post-infection with wild-type C. albicans cells." (PMID 27088599, 2016). "In the case of interleukin-6 (IL-6), the concentration increased moderately during infection." (PMID 27247231, 2016). "Release of IL-6 in the early stages of the infection might interfere with the induction of a specific Th1 response, predisposing the parasites to proliferate and cause disease." (PMID 26814478, 2016). "Subsequently, spinal cord changes at 49 dpi were further evaluated on a molecular level showing that IL-6 mRNA transcription was significantly decreased in IL-10R blocked mice (group “IL-10R↓late/TMEV”) compared to isotype-treated animals following TMEV-infection (group “isotypelate/TMEV”)." (PMID 27611574, 2016). "On the day of infection, mice received the anti-IL-6 mAb, the isotype-matched control mAb, or PBS." (PMID 27783671, 2016). "Combined with our data, it is reasonable to postulate that the DENV-ADE infection may suppress the cellular antiviral response by suppressing not only early induction of ISGs but also the later IFN signalling with IL-10 or IL-6." (PMID 26923481, 2016). "Infection with KSHV up-regulates IL-6 expression, a known autocrine growth factor for KS cells." (PMID 27893764, 2016). "After normalized to organ CFU burden of infection, IL-6, GM-CSF, IFN-γ and IL-17 in the kidneys of mnn10 mutant infected mice were markedly higher than mice infected with parental or revertant strains (P < 0.01) (the actual cytokine values were shown in S7 Fig)." (PMID 27144456, 2016). "However, important questions remain including the timing of the production of IL-6, IL-21 and IL-27 during Tfh differentiation and the GC reaction in different contexts of infection and immunisation." (PMID 31557986, 2016). "We found that IL-6 and IL-10 were both released by hMΦ at 5 hour post-infection by M. tuberculosis and remained significantly detectable in the supernatant 24 hours post-infection (respectively)." (PMID 27384401, 2016).
infection (continued). "Infection of WT macrophages with N. caninum induced a marked production of IL-6 and TNF-α, and this response was partially suppressed in macrophages lacking Nod2, whereas IL-10 levels were increased in culture supernatants of Nod2−/− BMDMs at the initial replicative cycle of the parasite (8 h)." (PMID 27377650, 2016). "Importantly, several additional cytokines and chemokines secreted by CD4+ T cells, including IL-17 and IL-6, are proinflammatory and capable of recruiting immune cells to the genital tract during infection." (PMID 27600502, 2016). "Our results suggest an association between increased IL-6 and IL-10 levels and stages of infection pre-HAART, independent of the slow or rapid progression status of the patient." (PMID 27214135, 2016). "The opposite was true for IL-6 with increasing concentrations after the infection." (PMID 26799658, 2016). "In addition, the levels of IL-6 induced by A1142::Ref-K57orf13 at 6 h and 24 h post-infection were higher than those induced at respective time points by the A1142 parental strain." (PMID 27550826, 2016). "BCG induced IL-8 response and reached maximum at 72 h post infection while IL-6 was low throughout." (PMID 27014727, 2016). "Furthermore, TNFR1−/− and TNFR1-IL-6−/− mice showed only a weak increase of the antimicrobial peptide CRAMP after infection while in contrast IL-6−/− mice displayed CRAMP levels similar to the ones of WT mice." (PMID 27057100, 2016). "In addition, VANBT infection induced the proinflammatory cytokines interleukin-6 (IL-6) and IFN-γ with different peak times." (PMID 27814404, 2016). "We found that DOX provoked generation of TNF-α and subsequently caused the activation of NF-κB and iNOS and increased the expression of genes required to control infection and injury, such as IL-1β and IL-6, indicating severe inflammatory conditions in the brain." (PMID 27120616, 2016). "In our analysis, we observe that a subset of these cytokines reported to be present in the serum also show transcriptional upregulations in PBMCs by 4 days post-infection (IL6, IL1B, IL1RN, CCL8, CXCL10) and by 7 days post-infection (CCL2, CCL3, CSF1, TNF, CXCL1, FAS and CXCL8)." (PMID 27595844, 2016). "Therefore, we performed cell-based experiments to investigate if an infection with P. acnes affects the secretion of IL-6 and IL-8 from premalignant prostate cell." (PMID 27284286, 2016). "By two weeks after infection, lungs of pDC-depleted mice showed diminished levels of regulatory cytokines (TGF-β and IL-10), associated with increased levels of inflammatory cytokines such as IFN-γ, TNF-α, IL-12 and IL-6." (PMID 27992577, 2016). "Thus, after infection of hDFSCs or Ca9-22 with P. intermedia or T. forsythia accumulation of interleukins IL-6, IL-8 and IL-10 in the supernatant was quantified after 2 h, 4 h and 24 h of anaerobic co-culture (MOI = 100)." (PMID 27974831, 2016). "The signaling of these PRRs culminate in the activation of nuclear factor κB (NFκB) and the release of inflammatory cytokines such as TNF, IL-1β, and IL-6, resulting in an early innate immune response that is required for infection control and for host defense." (PMID 27597997, 2016). "However, at early as 3 h post‐infection (hpi), we observed increased bacterial loads in IL6−/− pMacs." (PMID 27980776, 2016). "Multivariate regression analysis identified two cytokines, IL-6 and IFN-γ, that significantly contributed to all tested regression models (host, pathogen, lung CFU, or survival) but only at a single time point during infection (at 24 h and 6 h postinfection for IL-6 and IFN-γ, respectively)." (PMID 26787718, 2016). "Due to this lower sensitivity, serum interleukin-6 (IL-6) could represent a more reliable marker of periprosthetic low-grade infection." (PMID 24821631, 2015).
infection (continued). "In support of this, we observed that P. mirabilis causes more tissue damage and larger induction of the pro-inflammatory cytokines IL-1α, IL-β, IL-6, and G-CSF than does E. coli in independent infection, while a mixed infection appears more similar to E. coli alone." (PMID 25568946, 2015). "In addition, it was noticed that IL-6 up-regulation in the sera of DV2-infected TLR6-/- mice subsided by day 5 post-infection while that of responsive wild-type mice remained up-regulated." (PMID 26226614, 2015). "Damage or infection to the endothelium causes ET-1 to bind to ETB receptors on smooth muscle cells and control the macrophages and its release of inflammatory cytokines such as tumor necrosis factor-alpha, interleukin-6, and interleukin-1." (PMID 26823980, 2015). "A study evaluating the correlation between HLA-DR expression in laryngeal mucosa and interleukin gene variation found that 12 of 13 SIDS cases (92%) with high HLA-DR expression, prone sleeping position, and sighs of infection prior to death had the IL-6 −176 CG/CC genotypes (p = 0.01)." (PMID 25750641, 2015). "Indeed, Irg1 inhibits TLR-triggered production of IL-6 and TNFα, both of which are the only two pro-inflammatory cytokines that are partially suppressed during infection." (PMID 26510639, 2015). "Interestingly, this increase in IL-1α is accompanied by a decrease in IL-6 expression, suggesting a shift in the nature of the response to these infections at later times." (PMID 26171605, 2015). "In addition, it was observed that IL-32 and IL-6 are up-regulated by aberrant epigenetic modification during IV infection." (PMID 26490959, 2015). "Additionally, increasing levels of IL-6 and IL-17 were also observed during the early course of infection." (PMID 26135397, 2015). "Interestingly, infection with N. gonorrhoeae significantly induced pro (IL-6 and TNF-α) and anti-inflammatory (IL-10) cytokines in M0-MФ." (PMID 26125939, 2015). "However, by 4 days post-infection, there was a dramatic reduction in IL-6 mRNA expression (1.45-fold change) that remained low throughout the 14 days post-infection." (PMID 26664962, 2015). "Conversely to what has been shown for E75CV1 the progression of the E75-infection resulted in a dramatic imbalance of the immune system by day 7 pi, with the significant up-regulation of 9 genes, namely: IL-5, IL-1β, IL-6, IL-8, IL-10,IL-21, IL-23, DEFB2 and TLR-3." (PMID 26589145, 2015). "nucleatum infection on IL-6 expression in mouse tongue tissue." (PMID 26158901, 2015). "In particular G-CSF and IL-6 reflected severity and might provide complementary information on the severity of the infection." (PMID 26407163, 2015). "Culture media were taken for measuring IL-6 concentrations after infection." (PMID 25788763, 2015). "Thus, TLR4 can upregulate the expression of cytokines, such as TNF-α, IFN-γ, IL-6, IL-8, IL-12, and IL-10, thereby increasing resistance to pathogen invasion and infection." (PMID 26576220, 2015). "For example, the Treg percentage decreased when IL-6 concentration peaked during early infection (14 days PI), indicating that a high concentration of this cytokine might suppress Treg development." (PMID 26599407, 2015). "IL-1β, together with TNF-α and IL-6, are thought to be important proinflammatory mediators in initiating and maintaining the inflammatory response to pathogen and disease development during infection." (PMID 26052324, 2015). "Together, these results indicate that infection, IFNγ and TNFα have negative effects on mitochondrial respiration, which is alleviated by IL-4, while IL-6 afforded some protection, but only against loss of complex-IV." (PMID 26481427, 2015). "IL-19, IL-10, IL-6, IL-27 and IL-5 also increased during late infection days." (PMID 26070790, 2015).
infection (continued). "Thus, as the concentration of IFNγ and TNFα increase during the latter time points of infection and clearance in WT mice, the concomitant increase of IL-4 and IL-6 appears to protect the mitochondrial functions of the colonic epithelium." (PMID 26481427, 2015). "IL-6 also may indirectly enhance infection and viral dissemination through recruitment of monocytes, which serve as viral targets." (PMID 26512687, 2015). "Due to its excellent sensitivity, IL-6 could be an optimal tool for diagnosing low-grade TKA infection." (PMID 24821631, 2015). "Interestingly, the levels of a number of Th1 (IFN-γ, TNF-α, GM-CSF) and Th2 (IL-5, IL-6) cytokines were significantly reduced following the PZQ+EDLF combined treatment as compared to infected untreated mice at the late stage of infection." (PMID 26191954, 2015). "Moreover, we did show a similar response from mammalian expressed endotoxin-free mS100A9 in vitro, and by adenovirus-mS100A9 infection in vivo, which resulted in the induction of IL-6 and IFNγ in a TLR4-dependent fashion." (PMID 25706559, 2015). "TNF-α and IL-6 are potent proinflammatory cytokines induced during inflammation progress, accompanied with interleukin-12 (IL-12) playing the essential role in immune defense against infection." (PMID 26538826, 2015). "Moreover, other groups have proved IL-6 is critical for controlling infection in mice challenged with high doses of intravenously delivered M. tuberculosiss." (PMID 26157429, 2015). "Upon infection, IL-6 production strongly contributes to host defense." (PMID 25884400, 2015). "It is tempting to speculate that targeting IL-6, which is already available in the clinic, may reduce the severity of inflammatory disease during infective episodes and/or reduce the tendency of infections to trigger an exacerbation of inflammation." (PMID 25601923, 2015). "In contrast with cerebellar IL-6, IL-10 concentrations were significantly increased in mice with high vitamin D3 supplementation that died during the acute phase of the infection compared with the animals that had received low or standard vitamin D3 supplementation (*P < 0.05)." (PMID 25563481, 2015). "In contrast to what we observed regarding the Chlamydia-induced IFN-β response, control reactions measuring IL-6 production in OE cells revealed that there were significant reductions in Chlamydia-induced synthesis of IL-6 throughout the course of infection in the JSH-23 treated cells." (PMID 25798928, 2015). "The relationship between laryngeal immune stimulation, clinical signs of slight infection prior to death, and high levels of IL-6 in CSF may indicate an interaction between the immune system and the CNS." (PMID 25750641, 2015). "This early increase was also seen for IL-6 secretion on the 3rd day of infection." (PMID 26135397, 2015). "A hallmark of age-associated chronic inflammation without an overt infection is the elevated levels of inflammatory biomarkers such as C-reactive proteins, interleukin-6 (IL-6), chemokines CCL2, CCL3, and CCL4 in blood." (PMID 25620312, 2015). "In contrast, we noted an increase in a subset of Th17-associated cytokines in the BAL, specifically IL-17, IL-6, G-CSF, and CCL4, and elevated levels of these cytokines were sustained even after the majority of the IFNγ response had subsided, i.e. day 14 post infection." (PMID 25849970, 2015). "Moreover, ELISA data showed that the IL‐6 protein was significantly enhanced in the culture medium post 1‐, 2‐, and 4‐h infection." (PMID 25214524, 2014). "Normal expression levels of TNF-α and IL-6 in the blood of healthy individuals aid the prevention of infection and enhance immune function; however, overexpression may result in injury to tissues." (PMID 25371725, 2014). "However, interleukin-6 is a very early marker, but levels can become normal even if infection continues." (PMID 25033045, 2014).
infection (continued). "IL-8 levels increase about 90 minutes after infection and peak at about 120 minutes in septic neonates, whereas its circulating concentration decreases significantly 48 hours after birth, likewise the kinetics of IL-6." (PMID 25614712, 2014). "Moreover, there was an overall significant decrease in IL-6 secretion from Cpn-infected THP1 cells over the entire time course of infection." (PMID 25540075, 2014). "As expected, TNF, IL-23, and IL-6 were produced during infection." (PMID 25309905, 2014). "Infection of monocytes and monocyte-derived DCs with chlamydial serovars Ba, D and L2 could induce detectable secretion of cytokines IL-8, IL-6, IL-1β, IL-10 and TNF." (PMID 25123797, 2014). "Hence, the heightened resistance of IL-6−/– mice cannot be attributed to a pivotal role for IL-17 during infection." (PMID 24185641, 2014). "While similar levels of TNF-α and IL-6 were released after infection with low dose C. pneumoniae or stimulation with 1 ng/mL LPS, low dose C. pneumoniae induced higher levels of IL-1β, IL-12p40 and IL-12p70 over time than LPS, which was shown to be statistically significant." (PMID 25488836, 2014). "Results indicated that peak TNF- α and substantial IL-6 expression at 3 hours post infection." (PMID 25299049, 2014). "There was a peak of cytokines IL-10, IL-13, IL-6 and IL-4, 17 weeks after infection." (PMID 24886277, 2014). "Finally, identifying the major contributor of IL-6 from a diverse range of cell types to this striking phenotype remains a key area of interest for further research in this infection setting." (PMID 24185641, 2014). "IL-6 increased from days 2 to days 6 and from days 12 to days 14 post infection." (PMID 24725777, 2014). "Expression of IL-6 and IL-8 in endothelial cells reached peak levels at 8 h post infection." (PMID 24886982, 2014). "Specifically, we tested whether miR-155 overexpression or inhibition prior to infection could alter the magnitude of F. tularensis-triggered TNFα or IL-6 secretion." (PMID 25295729, 2014). "It is tempting to speculate that the decreased intestinal IFN-γ and IL-6 levels following mutant as compared to parental strain infection might be indicative for shifted intestinal T cell populations in the absence of cj0268c which needs to further unraveled." (PMID 24587249, 2014). "Thus, an increased expression of IL-6 mRNA in brain tissue of mice infected with HSV was shown during the first three weeks after infection." (PMID 25147828, 2014). "Key inflammatory mediators such as IL-6, IP-10, G-CSF and GM-CSF are expressed during infection." (PMID 24699832, 2014). "Furthermore, cytokine secretion (IL-1β, IL-6, IL-8) appears to be maintained for an extended period of infection, suggesting that a more chronic or persistent infection can maintain the pro-inflammatory condition." (PMID 25540075, 2014). "Finally, vinculin and Rab5 knockdown reduced infection of S. aureus, phosphorylation of MAPKs and IL-6 expression in murine lungs." (PMID 24466349, 2014). "Similarly, the proinflammatory cytokines IL-1α and IL-6 were mainly up-regulated by the swH1N1 infection." (PMID 24708855, 2014). "Furthermore, cytokine secretion (IL-1β, IL-6, IL-8) appears to be maintained for an extended period of infection." (PMID 25540075, 2014). "Indeed, epithelial cells responded early to mycobacterial infection by secreting IL-6 and the anti-inflammatory IL-22, while the anti-inflammatory IL-10 increased two days after infection." (PMID 24489729, 2014). "From these studies it is known that infection of colon epithelial cells (CEC) with Salmonella typhimurium causes an increase in GSK3β-dependent β-catenin phosphorylation, leading to an upregulation of IL-6, IL-8, and Wnt2, via TLR5/NF-κB activation." (PMID 25136145, 2014). "DCs infection resulted in significant production of inflammatory cytokines IL-8 and IL-6." (PMID 25123797, 2014).